MB (myoglobin)
Diseases named in the same sentence as MB in open-access papers (continued):
Sharing a sentence is not in itself a finding about the gene and the disease.
acute kidney injury (176 papers, 2005 to 2026). Sudden and sustained deterioration of the kidney function characterized by decreased glomerular filtration rate, increased serum creatinine or oliguria. "The systemic presence of myoglobin can lead to its deposition in renal tubules, where the heme moiety exerts direct nephrotoxic effects, potentially causing acute kidney injury." (PMID 40635153, 2025). "Early markers, either functional ones like creatinine and urine output, or biochemical ones such as very high myoglobin, can signal risk before full renal failure is established." (PMID 41398626, 2025). "This condition typically results from direct muscle toxicity, impaired cellular energy production, or immune-mediated responses, leading to myoglobin release, which can damage the kidneys and cause myoglobinuric acute kidney injury (AKI)." (PMID 39872682, 2025). "The predominant mechanism of acute kidney injury in mild to moderate heat-related illnesses appears to be tubular damage caused by myoglobin." (PMID 39840004, 2024). "Myoglobin has the potential to cause acute kidney injury (AKI), and in severe cases, rhabdomyolysis can also be fatal." (PMID 39759753, 2024). "This activity causes the release of myoglobin into the bloodstream and affects kidney function by producing failure in the glomerular filtration, due to myoglobinuria with acute renal failure." (PMID 39330835, 2024). "Previous studies have shown that PKC-δ contributed to tubular cell injury associated with proteinuria, and acute kidney injury induced by myoglobin, vancomycin, and cisplatin." (PMID 38972937, 2024). "Measuring myoglobin levels is essential to identify and exclude patients at risk of acute kidney injury due to heat-related illnesses." (PMID 39840004, 2024). "Rhabdomyolysis or hemolysis leads to a sudden release of a high amount of potentially toxic heme pigment (myoglobin or hemoglobin) into the systemic circulation, which after glomerular filtration causes renal injury and renal failure." (PMID 39130933, 2024). "Damaged tissue also releases myoglobin, which can cause oxidative damage to kidney tubules and lead to acute kidney injury (AKI)." (PMID 37424016, 2023). "The myoglobin level was also strongly associated with the combined outcome of acute kidney injury and death at 90 d (adjusted odds ratio, 7.9; 95% CI, 1.61–38.89)." (PMID 37408574, 2023). "Aggressive volume expansion via intravenous fluids remains critical in preventing rhabdomyolysis-associated nephrotoxicity and myoglobin-induced acute renal failure." (PMID 37581198, 2023). "The lowest abnormal level of CK associated with acute kidney injury is 5000 U/L. Acute kidney injury caused by RM is associated with myoglobin." (PMID 36181079, 2022). "For stanford type A aortic dissection patients underwent total aortic arch replacement with frozen elephant trunk implantation, serum myoglobin can improve postoperative acute kidney injury risk classification." (PMID 35273980, 2022). "The consequent accumulation of myoglobin in the kidneys causes tubular necrosis and acute renal failure." (PMID 35214765, 2022). "Rhabdomyolysis is a life-threatening disease caused by releasing myoglobin from injured myocytes, which results in acute kidney injury." (PMID 36583174, 2022). "We also showed that myoglobin provoked acute kidney injury followed with large extent of renal damage was associated with strong nuclear expression of PAX8 in proximal tubular cells." (PMID 36140438, 2022). "Although this venom is injected into the skin, the systemic effect can lead to muscle damage and the released myoglobin would cause renal failure." (PMID 33466223, 2021). "Intravenous volume resuscitation was started to avoid myoglobin precipitation and tubule obstruction causing acute kidney failure." (PMID 34579193, 2021). "Elevated concentrations of muscle injury biomarkers, myoglobin and creatinine kinase (CK), are associated with muscle damage-related illness and acute kidney injury (AKI)." (PMID 34003295, 2021).
acute kidney injury (continued). "Rhabdomyolysis is well known to be associated with acute kidney injury, and one of the proteins that are used as markers of rhabdomyolysis and its associated acute kidney injury is myoglobin." (PMID 31805809, 2020). "MNMS results in damage of kidney function (10–15% patients have acute kidney failure) through rhabdomyolysis and potential nephrotoxin, which cause increase of myoglobin and creatine phosphokinase (CK)." (PMID 32993712, 2020). "Myoglobin released from muscle can cause vasoconstriction, tubular casts, and oxidative stress in the kidney, resulting in acute kidney injury (AKI)." (PMID 31905634, 2019). "Myoglobin precipitation or accumulation have been proposed to cause oxidant injury and even to cause acute renal failure (ARF) after crush injuries/reperfusion." (PMID 31752982, 2019). "The indirect effects cause nephrons to be overloaded by degraded proteins, including myoglobin from decayed tissue tubules, which result in secondary acute kidney injury; whereas direct effects cause damage to the kidney cells due to cytotoxicity." (PMID 29556251, 2018). "Rhabdomyolysis is associated with extensive muscle injury that is accompanied by the release of myoglobin, which causes severe oxidative damage, ultimately leading to acute kidney injury." (PMID 28704479, 2017). "Another important finding resulting from Ec use is acute kidney injury (AKI) due to myoglobin deposition in the kidney caused by rhabdomyolysis." (PMID 28678861, 2017). "Myoglobin is nephrotoxic and in humans, elevated levels of myoglobin in serum or urine are associated with a risk of acute renal failure and subsequent mortality." (PMID 27446941, 2016). "In our case, the diagnostic workup for acute renal failure and presumed septic shock identified the elevated myoglobin as an associated factor in the patient's acute renal dysfunction." (PMID 27375910, 2016). "Myoglobin, a component protein of skeletal muscle tissue, in large amounts, can cause renal failure by accumulating in the kidneys and preventing the proper function of that organ." (PMID 26693360, 2015). "A remarkable rise in myoglobin level is an indicator for the diagnosis of mamushi bite and suggests the risk of acute renal failure." (PMID 25866646, 2015). "In these cases, increased levels of creatine phosphokinase (CPK) and blood myoglobin due to rhabdomyolysis are remarkable and can cause acute renal failure." (PMID 25866646, 2015). "His elevated serum creatine kinase (CK), serum and urine myoglobin levels justified rhabdomyolysis as the cause of acute renal failure." (PMID 21085538, 2010). "Consequently, amputation can cause acute kidney injury due to the direct effects of heme products and the tubular obstruction caused by myoglobin and urate crystals." (PMID 39791687, 2025). "Myoglobin can cause direct renal tubular damage, while inflammation, fluid shifts, and vasoconstriction further compromise renal function, increasing the risk of acute kidney injury." (PMID 41018313, 2025). "Once the blood supply of these tissues is restored, the cell products, notably myoglobin, potassium, urate, and phosphate, are released into the systemic circulation, which causes acute kidney injury (AKI), electrolyte and metabolic disturbances, and multiple organ dysfunction syndrome." (PMID 40093017, 2025). "While we specifically analyzed the relationship between current flow type and cardiac or renal complications, it is important to note that renal failure is commonly linked to extensive muscle damage and systemic release of myoglobin, a well-documented sequela of high-voltage injuries." (PMID 40283489, 2025). "Breakdown of myoglobin from injured muscles may cause tubular epithelium slough and cast formation in the kidney, obstruction of renal blood flow, and finally, renal failure." (PMID 39372200, 2024).
acute kidney injury (continued). "For example, the release of myoglobin and toxic metabolites from damaged tissues along with renal hypoperfusion may facilitate renal tubular cast formation and finally cause acute renal failure." (PMID 39372200, 2024). "Myoglobin increases in the renal tubules and ultimately can cause renal failure." (PMID 38629092, 2024). "These harmful substances include high levels of potassium, phosphate, and myoglobin, which may cause cardiac instability, acute kidney injury (AKI), or disseminated intravascular coagulation." (PMID 35683602, 2022). "After adjusting for known acute kidney injury risk factors, logarithmically transformed preoperative serum myoglobin [OR = 1.58 (95% CI, 1.26–1.95), P < 0.001] and postoperative day 1 serum myoglobin [OR = 3.47 (95%CI, 2.27–5.29), P < 0.001] were associated with severe acute kidney injury." (PMID 35273980, 2022). "The resulting hyperkalemia causes acidosis, and myoglobin deposits in the distal renal tubules, which may result in acute kidney failure." (PMID 27579205, 2016). "Reperfusion of the limbs may cause further muscle damage and release of myoglobin, CK, and other intracellular muscle contents, which may in turn result in acute kidney injury." (PMID 26587045, 2015). "The etiology of acute renal failure in this case was due to a combination of prerenal secondary to severe dehydration and renal secondary to tubular damage caused by hypoperfusion and the toxic effect of myoglobin." (PMID 26124970, 2015). "The resulting hyperkalemia causes acidosis, and myoglobin deposits in the distal renal tubules, which may result in acute renal failure." (PMID 19946500, 2009). "Urinary alkalinization with sodium bicarbonate was implemented to mitigate the risk of myoglobinuric acute kidney injury (AKI) secondary to potential myoglobin precipitation." (PMID 41006954, 2025). "Especially, myoglobin causes renal tubular necrosis through various pathways, leading to acute kidney injury (AKI) in about 20–50% of patients with rhabdomyolysis." (PMID 40289172, 2025). "Rhabdomyolysis leads to the release of myoglobin, sarcoplasmic proteins, and electrolytes into the blood circulation causing acute kidney injury (AKI)." (PMID 38629092, 2024). "Toxic renal effects of myoglobin following rhabdomyolysis can cause acute kidney injury (AKI) with the necessity of kidney replacement therapy (KRT)." (PMID 38486159, 2024). "Acute kidney injury (AKI) is the main life-threatening complication of crush syndrome (CS), and myoglobin is accepted as the main pathogenic factor." (PMID 34148549, 2021). "Because both hemoglobin and myoglobin are involved in the occurrence of cardiac surgery-associated acute kidney injury (CSA-AKI), hemoperfusion may have an additional protective effect on the kidney and may contribute to the recovery of renal function after cardiac surgery." (PMID 33228727, 2020). "Acute kidney injury (AKI) is a common complication of RM, and the pathogenesis of RM-associated AKI includes tubular obstruction caused by myoglobin, myoglobin cytotoxicity by lipid peroxidation, and the production of reactive oxygen species." (PMID 33225908, 2020). "Kidney injury can cause renal failure, which is a serious complication of CS that can result from circulatory shock, renal afferent arteriolar vasoconstriction (urinary concentration), increased urinary myoglobin levels, or metabolic acidosis (urinary acidity)." (PMID 28871521, 2017). "For example, experimental rhabdomyolysis, in which large amounts of intracellular hemoproteins such as myoglobin are released, cause heme-dependent acute kidney injury (AKI)." (PMID 28420988, 2017). "Animals receiving cilastatin excrete more myoglobin in the urine and are more likely to recover from acute kidney injury." (PMID 41820509, 2026). "Rhabdomyolysis can be complicated by acute kidney injury due to myoglobin-induced nephrotoxicity and tubular injury, in addition to volume depletion related to fluid sequestration." (PMID 41694166, 2026).
acute kidney injury (continued). "Rhabdomyolysis-induced acute kidney injury (RM-AKI) is mediated primarily by myoglobin (Mb) toxicity, yet effective targeted therapies remain unavailable." (PMID 42185634, 2026). "Beyond etiologic complexity, RML could mark greater disease severity and adversely influence outcomes through downstream effects such as myoglobin-associated acute kidney injury (AKI), electrolyte disturbances, and systemic inflammation." (PMID 41584825, 2026). "In nonviral diseases, RIG-I can act as a DAMP sensor to promote inflammatory responses, such as being activated by myoglobin to promote NF-κB/caspase-3 signaling in the acute kidney injury model." (PMID 40175216, 2025). "After rhabdomyolysis, muscle tissue releases substances such as myoglobin, creatine kinase, and electrolytes into the bloodstream, potentially leading to acute kidney injury (AKI)." (PMID 40271506, 2025). "The combined effects of myoglobin-induced toxicity and inflammation can lead to acute tubular necrosis, a common cause of acute kidney injury (AKI), which is often associated with electrolyte imbalances, acidemia, organ dysfunction and increased systemic inflammatory response." (PMID 41398626, 2025). "This is because the large amount of released myoglobin is highly nephrotoxic and induces acute kidney injury (AKI), which can occur as a serious complication of rhabdomyolysis." (PMID 40646849, 2025). "Severe rhabdomyolysis is frequently accompanied by increased urinary secretion of myoglobin (myoglobinuria), which can lead to acute kidney injury (AKI) and a potentially life-threatening metabolic crisis." (PMID 40869978, 2025). "The patient presented acute renal failure due to ischemia in the arterioles, decreasing blood flow, and due to acute tubular necrosis, generated by myoglobin pigment released after rhabdomyolysis." (PMID 39575035, 2024). "Rhabdomyolysis is a critical medical condition characterized by the rapid breakdown of muscle tissue, releasing substances such as myoglobin and creatine kinase into the bloodstream, potentially leading to acute kidney injury." (PMID 39070364, 2024). "Patients must be well hydrated to enhance the excretion of myoglobin, which is toxic to nephrons and can lead to acute renal failure." (PMID 39246875, 2024). "Severe rhabdomyolysis accompanied with high levels of myoglobin is a critical condition leading to acute kidney injury and in consequence to the potential need of renal replacement therapy." (PMID 38907120, 2024). "Of the many complications of rhabdomyolysis, pigment (myoglobin)-induced acute kidney injury (AKI) is common, seen in up to 30% of cases, especially so when CK levels are more than 5000 IU/L." (PMID 39347336, 2024). "The proposed mechanisms for renal failure in RML include renal tubular obstruction due to myoglobin accumulation in the kidneys and free radical-mediated cytotoxicity, leading to tubular necrosis." (PMID 39635585, 2024). "Rhabdomyolysis, a potentially life-threatening condition, occurs when myoglobin is released from damaged muscle cells, leading to acute kidney injury (AKI)." (PMID 38911241, 2024). "Rhabdomyolysis is a severe condition characterized by the rapid breakdown of skeletal muscle tissue, releasing myoglobin, creatine kinase, and electrolytes into the bloodstream, potentially leading to acute kidney injury." (PMID 39070364, 2024). "Renal involvement of myositis was often considered a result of tubal blockage by myoglobin released from damaged muscle cells, leading to post-renal acute kidney injury." (PMID 38566087, 2024). "The myoglobin that is released can be nephrotoxic, leading to acute kidney injury (AKI) from the myoglobin that can obstruct and directly injure renal tubules." (PMID 39262534, 2024).
acute kidney injury (continued). "Systemic myotoxicity is characterized by increases in serum myoglobin concentration and creatine kinase (CK) activity, hyperkalemia, and also acute kidney injury; this is mainly due to myoglobin toxicity in the renal tubules that can cause death." (PMID 37511277, 2023). "However, the massive release of creatine kinase (CK) and myoglobin during acute phases of inflammation has been observed to cause acute kidney injury (AKI) in nearly half of patients with rhabdomyolysis." (PMID 37425322, 2023). "The correlations between serum myoglobin and acute kidney injury as well as the 30-day mortality were assessed." (PMID 35273980, 2022). "The later signs of muscle breakdown are hyperkalemia, elevated blood creatine phosphokinase (CK) and myoglobin levels, and dark-colored or “Coca-Cola” colored urine due to myoglobinuria, leading to acute renal failure and acute kidney injury." (PMID 36360420, 2022). "The higher the CK level, the greater the risk for acute metabolic complications, and with a greater release of myoglobin in severe muscle necrosis, the chance of acute kidney injury is very high." (PMID 36694885, 2022). "The myoglobin precipitates into the glomerular filtrate resulting in nephrotoxicity and acute kidney injury." (PMID 34437003, 2021). "Intravenous fluid resuscitation and oral hydration likely averted the development of acute kidney failure, in spite of significantly increased serum creatine kinase and myoglobin levels." (PMID 34579193, 2021). "Rhabdomyolysis is frequently occurring in critically ill patients, resulting in a high risk of acute kidney injury (AKI) and potentially permanent kidney damage due to increased myoglobin levels." (PMID 33509234, 2021). "Intravascular fluid depletion due to intramuscular fluid sequestration, renal vasoconstriction from cytokine release, and tubular obstruction from myoglobin are responsible for renal failure in rhabdomyolysis." (PMID 33684174, 2021). "Acute kidney injury in CS is characterized by acute tubular necrosis, formation of myoglobin casts, and dilation of distal convoluted tubules, followed by myoglobinuric nephropathy." (PMID 28871521, 2017). "Rhabdomyolysis can lead to renal failure by tubular obstruction from excess myoglobin, direct tubular injury, or vasoconstriction of renal blood vessels." (PMID 28745014, 2017). "Muscle cell destruction as evidenced by myoglobin elevation can induce potentially life-threatening acute renal failure." (PMID 28049514, 2017). "Myoglobin is rapidly released from necrotic muscle, while subsequent rapid renal clearance and high concentrations are associated with RML-induced renal failure." (PMID 27034948, 2016). "Ischemic rhabdomyolysis during vascular reconstructions provokes ’renal’ (parenchymal) type of acute renal failure, due to multifactorial mechanisms of myoglobin toxicity on the renal parenchyma." (PMID 25622967, 2015). "Specifically, CK is a more sensitive indicator of skeletal muscle injury and predictor of renal failure than myoglobin." (PMID 26587045, 2015). "Acute tubular necrosis and acute renal failure occur as a result of myoglobin precipitation into the nephron." (PMID 25120938, 2014). "On the other hand, the patient had extremely high level of serum CK, accompanied by increased myoglobin and acute renal failure." (PMID 24207015, 2013). "Acute kidney injury results from impaired perfusion and intratubular obstruction by myoglobin and uric acid." (PMID 23956754, 2013). "The presentation of this multifactorial and multicausal syndrome varies from an asymptomatic but detectable elevation of CK and myoglobin in blood to a life-threatening condition with fulminant acute renal failure." (PMID 23497406, 2013). "Rhabdomyolysis may result in acute kidney injury (AKI) partly due to direct toxic effect of myoglobin in the kidneys." (PMID 40416436, 2025). "Myoglobin is toxic to the tubular cells of the kidney and can lead to renal failure." (PMID 40591365, 2025).